RN7SL116P (RNA, 7SL, cytoplasmic 116, pseudogene)
Gene: Miscellaneous RNA gene on chromosome 20 (38,872,770 to 38,873,074, forward strand). Ensembl gene ENSG00000240474.
Homologues: Orthologues: chimpanzee Metazoa_SRP (98% identical), macaque Metazoa_SRP (93% identical). Paralogues in human: RN7SL1 (78% identical), RN7SL3 (78% identical), RN7SL2 (77% identical), RN7SL5P (75% identical), RN7SL230P (73% identical), RN7SL126P (72% identical), RN7SL650P (72% identical), RN7SL296P (72% identical), RN7SL732P (72% identical), RN7SL414P (71% identical), RN7SL45P (71% identical), RN7SL4P (71% identical), and 700 more.